STAT3 (signal transducer and activator of transcription 3)
Diseases named in the same sentence as STAT3 in open-access papers (continued):
Sharing a sentence is not in itself a finding about the gene and the disease.
memory impairment (22 papers, 2017 to 2025). "Previous studies have shown that Aβ-dependent inactivation of JAK2/STAT3 axis in hippocampal neurons causes cholinergic dysfunction through presynaptic and postsynaptic mechanisms, leading to AD-related memory impairment." (PMID 39546459, 2024). "The Aβ-dependent deactivation of the JAK2/STAT3 axis in hippocampal neurons results in cholinergic dysfunction through both pre- and post-synaptic mechanisms, contributing to memory impairment associated with AD." (PMID 38259497, 2023). "Given that disturbed STAT3 activity by aging and the neurotoxic amyloid causes memory impairment related to AD, STAT3 activation will provide a novel therapeutic strategy for AD." (PMID 36614305, 2023). "Significantly, memory impairments caused by Aβ have been linked to the inactivation of the JAK/STAT3 signalling pathway, with pSTAT3 levels age-dependently decreasing in AD." (PMID 35562959, 2022). "Especially, IL-6 is known to activate STAT3, which is associated with memory impairment in the LPS-injected IL-6 KO mice." (PMID 30781690, 2019). "However, some studies have observed that the levels of p-STAT3 in hippocampal neurons decrease with age in AD mouse models and patients and that the inactivation of JAK2/STAT3 by Aβ is associated with memory impairment related to AD." (PMID 39936960, 2025). "Amyloid β (Aβ)-dependent inactivation of the JAK2/STAT3 axis in hippocampal neurons has been reported to cause cholinergic dysfunction through presynaptic and postsynaptic mechanisms, leading to AD-associated memory impairment." (PMID 39546459, 2024). "In conclusion, this is a novel pathway accounting for pathological dysfunction in AD, such as amyloid- and age-dependent inactivation of the JAK2/STAT3 axis in the hippocampal neurons causing memory impairment related to AD by disturbing cholinergic neurotransmission." (PMID 36614305, 2023). "More importantly, the implementation of a targeted STAT3 knock‐out in excitatory neurons results in a decrease in the progression of seizures and hippocampal memory impairments." (PMID 40103702, 2025). "Further, the implementation of a targeted STAT3 knock‐out specifically in excitatory neurons leads to a decrease in the course of seizures and the manifestation of memory impairments in the hippocampus." (PMID 40103702, 2025). "It is noteworthy that therapeutic effects of GZFL on memory impairment are depended on the inhibition of neuroinflammatory responses by the blockage of JAK2/STAT3 signaling pathway." (PMID 37465679, 2023). "In vitro and in vivo studies have demonstrated that the accumulation of tau can cause the inactivation of STAT3, which in turn inhibits the expression of N-methyl-d-aspartate receptors (NMDAR), and subsequently caused memory impairment." (PMID 37927608, 2023). "A study observed the IL-6 pathway activation in the hypothalamus and hippocampus in AD model mice, while inhibiting the signal transducer and activator of transcription 3 (STAT3) ameliorates memory impairment and reduces plasma IL-6 levels." (PMID 36293430, 2022). "Progressive evidence supports the pivotal role of STAT3 as an upstream regulator of the pathogenesis of AD-related memory impairment." (PMID 34069842, 2021). "Blocking the JAK2/STAT3 axis in hippocampal neurons leads to cholinergic dysfunction, which results in memory impairments in patients with neurodegenerative diseases." (PMID 33833662, 2021). "We also found that overexpressing STAT3 improved the hTau-induced memory impairments shown as less average latency to reach the previous target quadrant, more times across the target quadrant than the hTau mice." (PMID 33859760, 2021). "Neutralization of IL-6 and inhibition of the signal transducer and activator of transcription 3 (STAT3) signaling in the brains of AD mouse models alleviated memory impairment and peripheral glucose intolerance, and normalized plasma IL-6 levels." (PMID 33911072, 2021).
memory impairment (continued). "Here, we also found that overexpressing STAT3 attenuated hTau-induced synaptic and memory impairments by increasing NMDAR expression." (PMID 33859760, 2021). "We previously found that in transgenic mice overexpressing IL-32β, the phosphorylation of STAT3 was reduced, as were the levels of several cytokines, which reduced the memory impairment." (PMID 30781690, 2019). "Next, targeting IL-6 signaling, such as STAT3, could alleviate memory impairment and glucose intolerance in AD, and exercise may serve as a STAT3 inhibitor to improve this condition." (PMID 40843259, 2025). "However, recent research has shown that the neutralization of IL-6 and the inhibition of the STAT3 signaling pathway in the brain of AD mouse models can improve memory impairment." (PMID 39286235, 2024). "Considering that disrupted STAT3 activity due to aging and the neurotoxic effects of amyloid contribute to memory impairment associated with AD, the activation of STAT3 emerges as a novel therapeutic strategy for the condition." (PMID 38259497, 2023). "Thus, while the pharmacological inhibition of STAT3 by AG490 prevented memory decline in AβO-infused mice, it is noteworthy that AG490 per se caused memory impairment in control animals." (PMID 33911072, 2021). "Based on our confirmation that STAT3 inhibitors induce CREB activation through the ERK signaling pathway, we aimed to investigate whether STAT3 inhibition regulates the expression of ERK/CREB-related IEGs in neuronal cells as a potential mechanism for ameliorating memory impairments." (PMID 39648181, 2024).
myocarditis (22 papers, 2012 to 2025). Myocarditis is a condition that is characterized by inflammation of the heart muscle (myocardium). "Accordingly, heart samples from human myocarditis patients clearly showed a massive infiltration of inflammatory cells, associated with strong STAT3 activation as assessed by IHC with phospho-specific STAT3 antibodies." (PMID 23460527, 2013). "Furthermore, cardiomyocyte-specific transgenic expression of SOCS1 inhibits JAK/STAT3 activation in enterovirus-induced myocarditis, but this is associated with increased mortality in mice, highlighting a complex interplay." (PMID 38495094, 2024). "The in vivo administration of HJC0152, a pharmaceutical STAT3 inhibitor, mitigated the viral-induced AP and myocarditis pathology via increasing the IFNβ as well as ISG expression on day 3 p.i. and reducing the viral load in multi-organs." (PMID 39201692, 2024). "The pharmaceutical inhibition of STAT3 exhibits a therapeutic effect against viral pancreatitis and myocarditis via efficient, early viral clearance." (PMID 39201692, 2024). "In a transverse aortic constriction (TAC)-induced mouse heart failure model, inhibiting IL6/gp130/STAT3 with raloxifene alleviated TAC-induced myocarditis, cardiac remodeling and dysfunction." (PMID 38495094, 2024). "We also revealed that STAT3 is activated in adult mammalian cardiomyocytes in myocarditis and contributes to cardiomyocyte proliferation and, as a result, to the functional and structural recovery from myocardial injury." (PMID 38040660, 2023). "Previously, we reported that STAT3 plays an important role in the healing process of myocarditis with cardiomyocyte proliferation." (PMID 38040660, 2023). "Overall, these findings demonstrated that activated STAT3 achieved protective action in CVB3-induced myocarditis through survivin." (PMID 33658937, 2020). "From this, we can determine that survivin serves as a mediator of STAT3 anti-apoptosis in CVB3-induced myocarditis." (PMID 33658937, 2020). "The use of siRNA-CD11b to block CD11b function significantly attenuated mouse CVB3-induced myocarditis with the reduction in proinflammatory factors and signaling molecules including IL-17, IL-23 and STAT-3." (PMID 33817288, 2020). "STAT3 is also important for the differentiation of Th17 cells, which play a major role in the initiation and development of myocarditis." (PMID 30619368, 2018). "On the other hand, STAT3 contributes to immune-mediated myocarditis due to IL-6-induced complement component C3 production in the liver, as well as the differentiation of Th17 cells, which play a role in initiation and development of myocarditis." (PMID 30619368, 2018). "Evidence indicates STAT3 couples to potent protective innate immune response in the context of myocarditis." (PMID 30619368, 2018). "Other cell types are involved in the pathogenesis of myocarditis as well, further complicating the role of STAT3." (PMID 30619368, 2018). "STAT3 signaling was also found to attenuate myocarditis by polarizing macrophages to a less inflammatory phenotype." (PMID 30619368, 2018). "The Person correlation analysis showed that on day 7, the TNF-α and IL-6 levels in the myocarditis, nicotine and methyllycaconitine groups were negatively correlated with their corresponding p-STAT3 levels." (PMID 25396421, 2014). "Compared to the control group, the levels of p-STAT3 were increased in the nicotine, myocarditis and methyllycaconitine group on day 7, and were highest in the nicotine group, followed by the myocarditis group and the methyllycaconitine group." (PMID 25396421, 2014). "Further, we demonstrate that STAT3 is sufficient when constitutively active for triggering the onset of auto-immune myocarditis, involving enhanced complement C3 production and IL-6 signalling amplification in the liver." (PMID 23460527, 2013).
myocarditis (continued). "To assess the role of STAT3 in the development of immune-mediated myocarditis, we utilized the well-established EAM model, where heart disease is induced by means of immunization with an α-myosin peptide." (PMID 23460527, 2013). "Further, we demonstrate that STAT3 is sufficient when constitutively active for triggering the onset of immune-mediated myocarditis, involving enhanced complement C3 production and IL-6 signalling amplification in the liver." (PMID 23460527, 2013). "This appears to be relevant to disease pathogenesis in humans, since acute myocarditis patients display significantly elevated circulating IL-6 and C3 levels and activated heart STAT3." (PMID 23460527, 2013). "In conclusion, the present study revealed new insights in the protective function of STAT3 expressed in cardiomyocytes after CVB3-induced myocarditis." (PMID 22675647, 2012). "To study the relevance of the signal transducer and activator of transcription molecule 3 (STAT3) in CVB3-induced myocarditis, we examined mice with a cardiomyocyte-restricted STAT3 deletion." (PMID 22675647, 2012). "Interestingly, the protein expression level of HMGB1, an alarmin that activates the IL-6/STAT3 signaling pathway, was significantly higher (1.6 folds; *** p < 0.001) in endomyocardial biopsies from patients diagnosed with myocarditis compared to controls." (PMID 39200277, 2024). "Considering that adult cardiomyocytes proliferate in myocarditis in a STAT3‐dependent manner, it would be informative to examine whether STAT3/Runx1 is activated by inflammatory reaction in adult cardiomyocytes." (PMID 38040660, 2023). "Moreover, the role of IL-6/STAT3 cascade in adult mammalian is also implicitly exemplified in a self-limited model of myocarditis in which compensatory proliferation of pre-existing cardiomyocytes was triggered by robust activation of STAT3 activity." (PMID 35101092, 2022). "Our study showed that YQWY decoction could attenuate MTAC-induced myocardial inflammation, fibrosis, apoptosis, and reverse the impairment of cardiac function in rats by activating the IL-10/Stat3 signaling pathway and improving myocardium remodeling." (PMID 33456490, 2020). "Bazedoxifene inhibits IL-6/STAT3 signaling in cancer cells, but its effect on the Th17 immune response induced by myocarditis remains unknown." (PMID 33643041, 2020). "STAT3 signaling plays a protective function in Coxsackievirus B3-induced myocarditis." (PMID 32201498, 2018). "Collectively, these results indicate that STAT3 acts not only as a protective factor but also as a proliferative factor in adult mammalian cardiomyocytes, contributing to cardiac repair/regeneration from myocarditis-induced damage." (PMID 28469272, 2017). "This is the first demonstration that activation of STAT3 plays important roles in the myocardial recovery from myocarditis-induced damage in adult mammalian hearts, providing mechanistic insights into the self-limiting nature of myocarditis." (PMID 28469272, 2017). "In addition, levels of the signaling protein phosphorylated STAT3 were higher in the nicotine group and lower in the methyllycaconitine group compared with the untreated myocarditis group." (PMID 25396421, 2014). "STAT3 inhibition was effective and resulted in protection of mice from myocarditis, as shown by the significantly reduced percentages of heart-infiltrating CD11b+ cells at sacrifice and by virtually undetectable lymphocyte infiltration as assessed by H&E and anti-CD18 staining." (PMID 23460527, 2013). "Therefore, the cardiomyocyte-restricted KO was chosen to study the protective function of STAT3 against CVB3-induced myocarditis in vivo." (PMID 22675647, 2012). "Importantly, our results suggest that myocarditis might promote regeneration at least partially by stimulating HMGB1/IL-6/STAT3-dependent NGC proliferation." (PMID 39200277, 2024).
myocarditis (continued). "Indeed, the transcription factor STAT3 by its protective cardiac function, helping maintain metabolic homeostasis, may contribute to myocarditis due to enhanced cardiac IL-6 production and thereby IL-6-induced complement component C3 production." (PMID 31844116, 2019). "Thus, constitutively active STAT3 enhances Th17 function, which in turn might contribute to exacerbate myocarditis by maintaining inflammation and increasing tissue damage." (PMID 23460527, 2013). "Moreover, the therapeutic effects of STAT3 neutralization in EAM suggest that this factor may also play a role in myocarditis progression to DCM." (PMID 23460527, 2013). "Consequently, we here demonstrate the protective function of STAT3 in CVB3-induced myocarditis." (PMID 22675647, 2012). "Our findings identify STAT3 as an antagonizing factor of the IFN-STAT1 signaling pathway and provide a potential therapeutic target for viral-induced AP and myocarditis." (PMID 39201692, 2024). "This further confirmed that CVB3 could stimulate the expression of p-STAT3, and suggested that the p-STAT3 might be related to the pathogenesis of CVB3-induced myocarditis." (PMID 33658937, 2020). "Thus, aberrant IL-6/STAT3-mediated induction of liver acute phase response genes including C3, which occurs as a consequence of pre-existing inflammatory conditions, might represent an important factor determining the degree of myocarditis and its clinical outcome." (PMID 23460527, 2013).
Nephropathy (22 papers, 2017 to 2025). A nonspecific term referring to disease or damage of the kidneys. "Furthermore, activation of the JAK2/STAT3 pathway has been implicated in uric acid-induced kidney damage and the overproduction of inflammatory cytokines." (PMID 40170729, 2025). "Previous studies have implicated the JAK2/STAT3 signaling pathway and downstream IL-6 in uric acid-induced kidney injury, highlighting potential strategies for preventing and treating hyperuricemia-associated kidney damage." (PMID 40170729, 2025). "Several studies have shown that the JAK2/STAT3 signaling pathway is involved in hyperuricemia-induced nephropathy and that inhibiting this pathway can improve hyperuricemia-induced renal injury and fibrosis." (PMID 40361044, 2025). "Another powerful therapeutic target in the development of kidney damage is the signal transducer and activator of transcription 3 (STAT3)/PIK3R1/mechanistic target of rapamycin (mTOR) axis." (PMID 41318413, 2025). "In the STAT3 signaling pathway, the inhibition of STAT3 in tubular epithelial cells prevents kidney fibrosis and nephropathy in streptozotocin (STZ)-induced diabetic mice." (PMID 40149644, 2025). "Recent research has demonstrated that hyperuricemia can activate the JAK2/STAT3 signaling pathway in the kidney, thereby contributing to the pathogenesis and progression of hyperuricemia-induced nephropathy." (PMID 40361044, 2025). "We further applied scRNA‐seq to elucidate the therapeutic mechanism of BL23 acupuncture in HUA‐induced nephropathy and explored the potential association of this alteration with NLRP3 inflammasome and JAK2/STAT3 signaling pathways." (PMID 41278550, 2025). "Some proinflammatory factors such as TNF‐α not only promote cell apoptosis and enhance kidney damage, but also activate inflammatory signaling pathways such as STAT3 and NF‐κB to trigger the inflammatory response." (PMID 35734954, 2022). "Inhibiting STAT3 in tubular epithelial cells has also been shown to prevent kidney fibrosis and nephropathy in streptozotocin-induced diabetic mice." (PMID 34434118, 2021). "The results showed that EDA inhibited the expression of p-JAK2, p-STAT3 and p-STAT1, accompanied by downregulation of the expression of Bax and caspase-3, and significantly ameliorated kidney damage caused by ischemia–reperfusion injury (IRI)." (PMID 32620154, 2020). "In various experimental and human nephropathies, signal transducer and activator of transcription (STAT3) activation has been reported in the injured kidney, showing a profibrogenic role." (PMID 33212804, 2020). "In db/db diabetic mice, we found an enhanced senescence level combined with low expression of MBNL1 and miR-130a-3p and high expression of STAT3 compared with db/m control mice during nephropathy development." (PMID 32104542, 2020). "It has been shown that inhibition of the JAK/STAT3 pathway reduced infiltration of interstitial inflammatory cells and production of chemokines in the adriamycin-induced nephropathy model." (PMID 29682583, 2018). "Above all, scRNA‐seq analysis demonstrated that EA exerts anti‐inflammatory effects and reduces the IL‐1β expression in treating HUA‐induced nephropathy through downregulation of both the NLRP3 inflammasome and the JAK2/STAT3 signaling pathway." (PMID 41278550, 2025). "In this study, the extent of kidney damage in the non-treated CKD group, which was more than 4.5-fold higher than controls, was significantly reduced with DTBN treatment, in association with a decrease in key proinflammatory mediators (IL1, IL6, NFkB and STAT3)." (PMID 38555397, 2024).